PDCD4 (programmed cell death 4)
Diseases named in the same sentence as PDCD4 in open-access papers (continued):
Sharing a sentence is not in itself a finding about the gene and the disease.
cancer (continued). "Here we reported that PDCD4 might be another mediator in DTL regulating cancer cell proliferation." (PMID 31409387, 2019). "PDCD4 cDNA and PDCD4 specific siRNA also might be useful drugs for the cancer therapy." (PMID 31075975, 2019). "Moreover, PDCD4 could improve the sensitivity of cancer cells to chemotherapy drugs such as docetaxel and cisplatin." (PMID 30519392, 2018). "However, despite these advances in our understanding of the essential role of PDCD4 in cancer progression, the precise molecular mechanism through which PDCD4 is downregulated during tumorigenesis remains largely unknown." (PMID 27647131, 2016). "Therefore, miR-21 and PDCD4 are potential targets for novel cancer prevention and therapeutics." (PMID 27323401, 2016). "Because of the association between PDCD4 and cancer differentiation, PDCD4 restoration could be a novel approach for differentiation cancer therapy, resulting in effective suppression of solid tumor development and further improving the prognosis." (PMID 27852288, 2016). "Furthermore, the subcellular localization of the PDCD4 protein affects cancer behavior." (PMID 27852288, 2016). "However, PDCD4 is likely a multifunctional protein, whose role in cancer is only partly understood." (PMID 25177545, 2014). "PDCD4 has been widely studied as anti-cancer therapeutic target [Lankat-Buttgereit and Goke, 2009]; its role however as a translation inhibitor in inflammation, cell invasion and smooth muscle contraction could be indicative of its implication in the expression of the asthmatic phenotype." (PMID 23606399, 2013). "However, relatively little is known about mechanisms regulating PDCD4 expression in cancer cells." (PMID 20602797, 2010). "MiR-21 is a microRNA overexpressed in numerous types of cancer and which activates PI3K/AKT pathway by down-regulating its main targets, PTEN and PDCD4." (PMID 40004462, 2025). "Inhibit the expression of PDCD4 in macrophages, activate PI3K/AKT/mTOR signaling pathway, and induce the polarization of M2 macrophages, thus promoting cancer metastasis." (PMID 38188683, 2023). "A total of 20 target mRNAs of three miRNAs were predicted, among which seven target mRNAs—ASAP3, BCL2L2, LMF1, PPM1L, PTPN21, SLC18A2, and NR3C2—had prognostic value; PRKACB, PDCD4, RPS6KA5, and BCL2L2 were enriched in the miRNA cancer pathway." (PMID 36829221, 2023). "While, the expression levels of PDCD4 and FOXO3 were significantly upregulated in both cell types treated with Car-NIO, Mel-NIO, and olaparib in comparison with untreated cancer cells." (PMID 37808196, 2023). "miRNA-183 targets programmed cell death 4 (PDCD4) and Fork-head box O3 (FOXO3) to increase proliferation and invasion in human carcinoma." (PMID 37808196, 2023). "From the lncRNA-mRNA pathway network, PYCARD, RIPK2, and CASP1 were found to be significantly enriched in the NOD-like receptor signaling pathway, whereas MAP2K2, LUM, RPS6, PDCD4, TWIST1, and HIF1A were significantly enriched in proteoglycans in cancers." (PMID 36619896, 2022). "Other studies have also found that miRNAs can affect the proliferation and migration of cancer cells by regulating the expression of TP53INP1 and PDCD4." (PMID 35723348, 2022). "This presumably occurs through the downregulation of tumor suppressor genes such as PDCD4 with an impact on eIF4A and the PERK/Nrf2 axis, thus promoting the survival of cancer cells." (PMID 36552834, 2022). "Accordingly, over-expression of miR-21 in human cancers results in a decreased level of the tumor-suppressor proteins PTEN, PDCD4, SPRY2, and/or RECK, thereby promoting cell proliferation." (PMID 34066762, 2021). "Therefore, PDCD4 could be considered as a cancer therapy target." (PMID 33304903, 2020). "miR-21 is involved in fibrosis as part of the transforming growth factor (TGF-β) induced fibrosis pathway, and targets programmed cell death-4 (PDCD4) to sustain cell survival, cancer cell invasion and metastasis." (PMID 30999696, 2019).
cancer (continued). "MiR-21-5p is a well-studied “oncomiR” in multiple types of cancers with PTEN, PDCD4 and RECK as its best-known target genes." (PMID 30736829, 2019). "Experimental evidence demonstrated that miR-21 is able to promote cancer through inhibition of several genes, such as phosphatase and tensin homologue (PTEN) on chromosome 10, tropomyosin-1 (TPM1), and programmed cell death-4 (PDCD4)." (PMID 29914173, 2018). "Overexpression of miR-21 is known to induce EMT by targeting PDCD4 and TIMP3 mRNAs in various cancer types, including ESCC." (PMID 29254151, 2017). "It has been suggested that miR-21 confers chemoresistance in cancer cells by regulating the expression of phosphatase and tensin homolog (PTEN) and programmed cell death 4 (PD4D4), and berberine sensitizes cancer cells through PTEN/Akt signaling pathway." (PMID 29113353, 2017). "In certain cancers, the interaction between MIR21 and PDCD4 is necessary for maximal AP-1 activation." (PMID 27084064, 2016). "Hence, suppressing PDCD4 could promote cancer migration and invasion." (PMID 27533461, 2016). "Four HNSCC cancer cell lines (SCC029b, SCC003, SCC099, SCC089) were screened by QRT-PCR to determine the relationship between miR-21 and PDCD4 expression." (PMID 26867589, 2016). "SRSF3 reportedly modulated the alternative splicing of several apoptosis-related genes, such as caspase-2 (Casp2), programmed cell death 4 (PDCD4), and homeodomain-interacting protein kinase-2 (HIPK2) in distinct cancer cells." (PMID 27983653, 2016). "Some previous studies have shown that UA can inhibit several cancer cells through multiple pathways, namely NF-κB, ASK1-JNK, STAT3, JNK and TGF-β1/miR-21/PDCD4 Pathways, and so on." (PMID 27708244, 2016). "We show that miR-21 and miR-499 directly interact with the 3’UTR of PDCD4 in both HEK-293 and tonsil cancer cell lines." (PMID 26867589, 2016). "The peptide was effective in inhibiting cancer cell invasion, migration and proliferation and activating apoptosis by modulating miR-21 targets, including PTEN and PDCD4." (PMID 25824952, 2015). "The tumor suppressor genes, programmed cell death 4 (PDCD4) and phosphatase tensin homologue (PTEN), which target miR-21, are underexpressed in several types of cancer." (PMID 24959246, 2014). "Previous studies have shown that the inhibition of miR-21 in cancer cells increases PTEN and PDCD4 protein levels in HeLa and MCF-7/ADR cells." (PMID 24959246, 2014). "So far, validated targets of mir-21 included programmed cell death 4 gene (PDCD4), tropomyosin 1 (TPM1), phosphatase and tensin homolog (PTEN), chromosome condensation protein G (NCAPG), reticulon 4 isoform A (RTN4) and other cancer-related genes." (PMID 25098165, 2014). "Programmed cell death 4 (PDCD4), originally identified as the neoplastic transformation inhibitor, was attenuated in various cancer types." (PMID 22272332, 2012). "PDCD4 also represents a previously unknown signaling target of chemokine receptors; therefore, these observations increase our understanding of alternative pathways to migration that may be activated or inhibited by chemokines in the context of cancer cell survival." (PMID 20661426, 2010). "mir-21 was found to be over expressed in multiple cancers down regulated tumor suppressor genes (TPM1, PTEN, PDCD4 BASP1 and RTN4) in invasion and metastasis of cancer." (PMID 21114830, 2010). "Mean expression in carcinoma specimens compared to the control group was measured for MASPIN, PDCD4, GLCCl1, BMPR-II, and APAF-1." (PMID 20331864, 2010). "miR-21 has been shown to have proliferative, metastatic, and anti-apoptotic functions in cancer by targeting genes such as PTEN, TPM1, Pdcd4, and maspin." (PMID 19440450, 2008). "Similarly, Phosphatase and Tensin Homolog (PTEN) and Programmed Cell Death 4 (PDCD4) are direct targets of miR-21, evidenced to be downregulated, and support the cancer phenotype in NSCLC." (PMID 40863728, 2025).
cancer (continued). "Although the suppression of PDCD4 can have notable impacts on the behavior of cancer cells, there is still no conclusive evidence that it specifically targets and eliminates CSCs." (PMID 38891090, 2024). "In addition, an increased expression of NANOG ⇒ STAT3 ⇒ miR21 was followed by the down-regulation of programmed cell death 4 (PDCD4), resulting in the enhanced anti-apoptotic and chemoresistance properties of cancer cells." (PMID 36497144, 2022). "Regardless of the cancer types, genes such as ITGA5, SERPINE1, EIF4EBP1 are majorly associated with bad outcomes; while genes such as ALDH2, DBP, FRAT1, PDCD4 are associated with good outcomes." (PMID 35197510, 2022). "For instance, miR-21-5p could enhance the spread of HBC by targeting cancer suppressive genes, such as leucine zipper transcription factor like 1 (LZTFL1), programmed cell death 4 (PDCD4), and tropomyosin 1 (TPM1)." (PMID 34967265, 2022). "In our proposed DMD-related lncRNA-mRNA pathway networks, PYCARD, RIPK2, and CASP1 were significantly enriched in the NOD-like receptor signaling pathway, whereas MAP2K2, LUM, RPS6, PDCD4, TWIST1, and HIF1A were significantly enriched in proteoglycans in cancers." (PMID 36619896, 2022). "Therefore, the PDCD4/eIF4A/FAK signaling pathway constitutes a crucial basis for the discovery and characterization of novel cancer drug targets." (PMID 36552834, 2022). "In cancer cells, the increase in miR-21 expression levels was found to regulate different apoptotic genes and to down-regulate PTEN and programmed cell death protein 4 (Pdcd4), which are tumor suppressor proteins." (PMID 36559104, 2022). "Taken together, these results suggest that MAP2K2, LUM, RPS6, PDCD4, TWIST1, and HIF1A may play important roles in DMD pathophysiology by regulating the MAPK pathway and proteoglycans in cancer." (PMID 36619896, 2022). "It was shown that in cancer stroma miR-21 induces the TGF-β1-stimulated transdifferentiation of cultured fibroblasts into myofibroblasts by targeting Programmed Cell Death 4 (PDCD4), a significant negative predictor of collagen I expression." (PMID 34527667, 2021). "It has been widely established that miR-21 promotes survival and proliferation of cancer cells by directly inhibiting its targets, including PTEN, Programmed Cell Death 4 (PDCD4), reversion-inducing-cysteine-rich protein with kazal motifs (RECK), and sprouty RTK signaling antagonist 2 (SPRY2)." (PMID 34066762, 2021). "However, patients with both high PDCD4 and PRMT5 demonstrate poor prognoses, suggesting that arginine methylation of PDCD4 by PRMT5 decreases the ability of PDCD4 to suppress cancer cell growth." (PMID 34006904, 2021). "Despite its described role in selective mRNA translational mechanisms, the investigation of PDCD4 targets has been largely unexplored using genomics approaches, neither in cancer nor in neuronal models." (PMID 32747606, 2020). "Interestingly, miR-21 represses the expression of its target’s apoptotic peptidase activating factor 1 (APAF1) and programmed cell death 4 (PDCD4) to inhibit apoptosis and increase paclitaxel resistance in cancer cells." (PMID 32121073, 2020). "Overexpression of miR-21 in cancer interrupts apoptotic signalling and dampens drug sensitivity by direct downregulation of phosphatase and tensin homolog (PTEN) and programmed cell death protein 4 (PDCD4)." (PMID 32102476, 2020). "In addition to its role in cancer, MEG3 also functions as a ceRNA for miR-21 to regulate PDCD4 expression in ischemic neuronal death followed by reperfusion." (PMID 31620370, 2019). "We speculate that miR-21 in TNF-α mRNA positive cancer cells may suppress an autocrine effect of TNF-α to mediate cell death, e.g., via PDCD4." (PMID 30999696, 2019). "Moreover, programmed cell death protein 4 (PDCD4), inhibited by miR-150, was attributed to the suppression of cancer cell migration and invasion." (PMID 30833362, 2019).
cancer (continued). "MiR‐21 targets anti‐oncogenes and metastasis‐suppressing genes, like programmed cell death 4 (PDCD4), tumour‐suppressor gene tropomyosin 1 (TPM1), phosphatase and tensin homologue (PTEN) and Sprouty, thereby demonstrating its involvement in cancer growth, invasiveness and metastasis." (PMID 28799211, 2018). "miR-21 could repress the expression of its targets apoptotic peptidase activating factor 1 (APAF1) and programmed cell death 4 (PDCD4) to inhibit the apoptosis and confer chemoresistance of cancer cells." (PMID 29228644, 2017). "MicroRNA-21 (miR-21) is an oncogenic microRNA that regulates the expression of multiple cancer-related target genes, such as PTEN and PDCD4, and has been reported to be consistently up-regulated in various types of cancers, including colon, breast, lung, and stomach cancers." (PMID 25609245, 2015). "Targets of miR-21 in cancer include PTEN, PDCD4, LRRFIP1, RECK, TIMP-3, TPM1, BTG2, and Sprty2." (PMID 25366985, 2014). "Although these proteins have been previously linked to cancer cell survival, they have not been previously associated with CLL nor has PDCD4 been established as a downstream phosphorylation target of CXCL12 signaling." (PMID 20661426, 2010). "If a patient contains cancer cells like MCF-7 and CTC-ITB-01 at different sites, which are subjected to hypoxia to varying degrees, then these conditions may explain the variability of the PDCD4 levels in CTCs of the patients." (PMID 39890941, 2025). "Beyond its role in cancer, PDCD4 also participates in non-oncogenic processes." (PMID 41516182, 2025). "For example, erioflorin interferes with the interaction between β-TrCP1 and programmed cell death protein 4 (PDCD4) and stabilizes PDCD4 protein levels with a concomitant alteration of the cell cycle progression and suppression of the cell proliferation of various cancer cell lines." (PMID 37686524, 2023). "Efficient knockdown of miR-21 by CHAIN restored programmed cell death protein 4 (PDCD4) and reversion‐inducing‐cysteine‐rich protein with Kazal motifs (RECK) and further crippled downstream matrix metalloproteinases-2 (MMP-2), which undermined cancer proliferation, migration and invasion." (PMID 37284454, 2023). "miR-21 is not only upregulated in cRCC but is also involved in cancer progression (proliferation, migration, invasion, epithelial mesenchymal transition) and the cancer stem cell phenotype by targeting tumor suppressor genes such as PTEN, PDCD4, TIMP3 or LATS1." (PMID 36359921, 2022). "However, PDCD4 is not always downregulated in cancers, as expression has been found to be increased, decreased or remain unchanged in squamous lung carcinoma and it is highly expressed in proliferating cells in some carcinomas of the bladder and breast." (PMID 35847932, 2022). "Indeed, Arg110 methylation of PDCD4 by PRMT5 modulates PDCD4 subcellular translocalization from the nucleus to the cytoplasm and facilitates its interaction with eIF4A in the cytoplasm, leading to enhanced cancer cell viability." (PMID 34006904, 2021). "We noticed that the sample size for a particular cancer group was not large enough to define the prognostic value of PDCD4, and not having nucleus-specific PDCD4 protein measurements could also restrict the precise evaluation." (PMID 27852288, 2016). "In poorly differentiated carcinoma, PDCD4 expression was low or absent." (PMID 26252635, 2015). "The downstream changes in PDCD4 protein levels after miR-21 LNA transfections and BPA treatment suggests a new plausible mechanism for BPA toxicity in bovine GCs that is not unlike those seen in various cancers." (PMID 35955412, 2022).
infection (8 papers, 2013 to 2025). The state of being infected such as from the introduction of a foreign agent such as serum, vaccine, antigenic substance or organism. "Following infection of HeLa cells with rHerts/33, we observed a slight activation of p-Akt and a mild downregulation of PDCD4." (PMID 38377149, 2024). "Densitometry data clearly indicated that post-infection, there was a notable decrease in PDCD4 expression coupled with an increase in phosphorylated S6 (pS6) levels, indicative of mTOR pathway activation." (PMID 38912807, 2024). "As expected, we observed an MOI-dependent increase in PDCD4 degradation, with a more pronounced effect after 16 hours of infection." (PMID 38912807, 2024). "PDCD4 mRNA levels following 18 hour infection inversely correlated with miR-21 expression, and were significantly lower in IL-28R null mice compared to WT (p = 0.045)." (PMID 24098127, 2013). "In vivo 18 hours following infection with either pathogen, miR-21 was significantly reduced and PDCD4 increased in the lungs of wild type compared to IL-28R null mice." (PMID 24098127, 2013). "Infection of PDCD4 null mice with USA300 resulted in improved clearance, reduced pathology, and reduced inflammatory cytokine production." (PMID 24098127, 2013). "As predicted by our in vitro studies, in mice expressing IL-28R reduced levels of miR-21 at 18 hours post infection correlated with prolonged PDCD4 mRNA expression." (PMID 24098127, 2013). "A major effector of IFNλ signaling is PDCD4, which appears to be regulated by multiple pathways in response to infection." (PMID 24098127, 2013). "Our findings revealed a uniform trend in PDCD4 expression levels in TOSI cells infected with these strains at both 3 and 24 hours post-infection, highlighting the widespread and pronounced activation of mTOR activity and subsequent PDCD4 degradation in various mycobacterial infections." (PMID 38912807, 2024). "In agreement with the reduced protein abundance of AKT1 after MPXV infection, AKT1-regulated sites were less phosphorylated over the course of the infection, e.g., IRS1 pS629, PDCD4 pS457." (PMID 39117661, 2024). "On the other hand, genes linked to cell proliferation and apoptosis (e.g., BCL6, APOE, PDCD4, and RARES2) emerged as the top inhibited master molecules due to infection." (PMID 26865111, 2016). "To corroborate the endogenous levels of PDCD4, we compared our flow cytometry and microscopy data with Western blot results from RAW cells infected with various mycobacteria after 3 and 24 hours of infection." (PMID 38912807, 2024). "Furthermore, during infection with the second L. europaeus GI.2 genotype, the expression of PTEN and PDCD4 was downregulated in the kidneys and spleen compared to healthy rabbits." (PMID 38516020, 2024).
cardiovascular diseases (7 papers, 2014 to 2025). "The miR-21/PDCD4 pathway: PDCD4 is a pivotal regulator of cardiovascular diseases, affecting various cellular processes including apoptosis and proliferation." (PMID 40563948, 2025). "PDCD4 also plays a role in regulating cardiovascular diseases by inhibiting proliferation and inducing apoptosis of most cardiovascular cells, including VSMCs, cardiac myocytes, and fibroblasts." (PMID 35983977, 2022). "It was reported that oxidative stress-induced cell injury is also related to the PDCD4 expression in cardiovascular diseases." (PMID 35983977, 2022). "Accumulating evidence suggests that PDCD4 plays an important role in cardiovascular diseases." (PMID 24626527, 2014). "Similarly, many genes, including CALM2, PDCD4, TXNIP, CYP11B2, P2Y12, and ROCK1, have been identified as downstream targets of GAS5 in cardiovascular diseases." (PMID 38812041, 2024).
heart diseases (3 papers, 2013 to 2019). "In cardiac disease, functional assessment of miR-21 implicates PDCD4, SPRY1 or SPRY2, Phosphatase and tensin homolog, and Fas ligand as the major targets of miR-21." (PMID 23441172, 2013).
metabolic disorders (3 papers, 2016 to 2024). "Our prior studies have shown that Pdcd4 plays a detrimental role in metabolic disorders by inhibiting the transition of white adipose tissue to beige adipose tissue and facilitating the formation of stress granules." (PMID 38822367, 2024).